FGD1 (FYVE, RhoGEF and PH domain containing 1)
Description:
Activates CDC42, a member of the Ras-like family of Rho- and Rac proteins, by exchanging bound GDP for free GTP. Plays a role in regulating the actin cytoskeleton and cell shape.
Synonyms: FGDY; ZFYVE3; AAS; MRXS16
Tractability: Antibody: its Gene Ontology location is reachable by antibodies, with high confidence; the Human Protein Atlas places it where antibodies can reach. PROTAC: ubiquitination databases record sites on it; its protein half-life has been measured.
Target class: Other cytosolic protein
Gene: Protein-coding gene on chromosome X (54,445,454 to 54,496,234, reverse strand). Ensembl gene ENSG00000102302.
Subcellular location: Cytoplasm; Cell projection, lamellipodium; Cell projection, ruffle; Cytoplasm, cytoskeleton
Subcellular location (Human Protein Atlas): Cytosol; Plasma membrane
Pathways (Reactome):
Signal Transduction: CDC42 GTPase cycle; G alpha (12/13) signalling events; NRAGE signals death through JNK
Gene Ontology:
Molecular function: guanyl-nucleotide exchange factor activity; small GTPase binding; metal ion binding
Biological process: actin cytoskeleton organization; filopodium assembly; regulation of GTPase activity; animal organ morphogenesis; cytoskeleton organization; regulation of cell shape; regulation of small GTPase mediated signal transduction; signal transduction
Cellular component: cytosol; plasma membrane; cytoplasm; Golgi apparatus; lamellipodium; ruffle; cytoskeleton
Gene-disease validity (ClinGen):
ClinGen rates the evidence that FGD1 causes each of these diseases.
Aarskog-Scott syndrome, X-linked (X-linked): Definitive. Aarskog-Scott syndrome (AAS) is a rare developmental disorder characterized by facial, limbs and genital features, and a disproportionate acromelic short stature.
Homologues: Orthologues: chimpanzee FGD1 (99% identical), macaque FGD1 (99% identical), pig FGD1 (97% identical), rabbit FGD1 (96% identical), dog FGD1 (96% identical), rat Fgd1 (95% identical), mouse Fgd1 (95% identical), guinea pig FGD1 (94% identical), tropical clawed frog fgd1 (61% identical), zebrafish fgd1 (57% identical), Caenorhabditis elegans exc-5 (20% identical), Caenorhabditis elegans frm-3 (6% identical). Paralogues in human: FGD4 (39% identical), FGD3 (35% identical), FGD2 (32% identical), FGD6 (23% identical), FGD5 (20% identical), FARP2 (19% identical), FARP1 (17% identical), ECT2L (11% identical), ARHGEF39 (8% identical), FRMD7 (5% identical).
Diseases named in the same sentence as FGD1 in open-access papers:
FGD1 is named in the same sentence as 35 diseases in open-access papers, as found by Europe PMC text mining. Sharing a sentence is not in itself a finding about the gene and the disease. The quoted sentences say what the papers report.
Aarskog-Scott syndrome (13 papers, 2015 to 2025). "rs55975541 in CDC42BPG, a variant with damaging PolyPhen and SIFT predictions, was found to be enriched; CDC42BPG is downstream of CDC42, the direct downstream target of the causative gene of Aarskog syndrome, FGD1." (PMID 38785976, 2024). "Annually, two or three new cases are diagnosed with Aarskog–Scott syndrome, which is associated with FGD1 variants." (PMID 35911831, 2022). "A new FGD1 gene variant was revealed in this study, providing insights into the link between phenotype and genotype variations in Aarskog-Scott syndrome as well as a foundation for its diagnosis and treatment." (PMID 36051692, 2022). "In our study, c.1270A>G variant of FGD1 resulted in Aarskog–Scott syndrome, and the analysis of pathogenicity supports the deleterious effect of the variant." (PMID 35911831, 2022). "Aarskog–Scott syndrome is a genetically and clinically heterogeneous rare condition caused by a pathogenic variant in the FGD1 gene." (PMID 33762894, 2021). "Aarskog–Scott syndrome is an X-linked recessive genetic condition due to pathogenic variants in the FGD1 gene." (PMID 33762894, 2021). "Sufficient evidence has suggested that haploinsufficiency of the FGD1 gene causes Aarskog-Scott syndrome, which is characterized by hypogonadism and other abnormalities." (PMID 32381089, 2020). "Genome analyses on families affected by Aarskog syndrome have revealed a mutation in FGD1 (R402W at position 1204 (1204C > T) in 20% of the cases." (PMID 29925821, 2018). "This study reports a novel mutation in FGD1 in an Emirati family with two affected brothers, and these are the first fully characterized cases of Aarskog-Scott Syndrome from the country." (PMID 28103835, 2017). "Specifically, patients with Aarskog-Scott syndrome (AAS) carry rare mutations in the FGD1 gene." (PMID 29888248, 2018). "Aarskog-Scott syndrome is an X-linked condition caused by mutations of the FGD1 gene." (PMID 26848196, 2015). "This review raised the suspicion of Aarskog–Scott syndrome, and a molecular diagnosis was identified by a targeted reanalysis of the FGD1 gene (U103)." (PMID 30109123, 2018).
faciogenital dysplasia (10 papers, 2008 to 2024). "Loss-of-function mutations in the gene encoding FGD1 cause faciogenital dysplasia, a rare X-linked disorder that manifests in defects of bone development, craniofacial abnormalities, and mental retardation." (PMID 32673397, 2020). "Mutations in FGD1 are associated with faciogenital dysplasia (FGDY), which is characterized by skeletal defects that are comparable to the phenotype of Mlk3−/− mice." (PMID 27200351, 2016). "FGD1 is the causative gene for human faciogenital dysplasia that is characterized by short stature, facial abnormalities, and skeletal and genital anomalies." (PMID 26306008, 2015). "Mutations in human FGD1 cause faciogenital dysplasia affecting multiple skeletal structures including short stature." (PMID 26306008, 2015). "The family's name is derived from the founding member, fgd1, which causes faciogenital dysplasia in humans when mutated." (PMID 19308258, 2009). "Fgd1 (also known as faciogenital dysplasia) (Fragment: E020) shows different, yet significant trends in all three Adar-deficient tissues, that is, lesser inclusion in cortex and bone marrow whereas much higher inclusion is observed in the liver." (PMID 32727871, 2020). "FGD1 is a selective Cdc42 GEF, and mutations in the FGD1 gene are responsible for the X-linked disorder known as faciogenital dysplasia." (PMID 31766364, 2019). "Many GEFs for the Rho family members were originally identified as oncogenes; in contrast, FGD1, which contains DH and PH domains, was discovered by positional cloning as the gene responsible for faciogenital dysplasia (FGDY)." (PMID 18410521, 2008).
breast carcinoma (6 papers, 2012 to 2021). "FGD1 is overexpressed in human prostate and breast cancer and is associated with tumor aggressiveness." (PMID 31562322, 2019). "Over expression of FGD1 has also been previously associated with cancer progression in prostate and breast cancer." (PMID 28851357, 2017). "Increased expression of FGD1 serves as an oncogene in hepatocellular carcinoma, breast cancer and prostatic cancer." (PMID 34783295, 2021). "Our data demonstrate that the essential function of TKS5 in directing the formation of collagenolytic invadopodia in breast cancer cells requires FGD1, probably through the direct modulation of CDC42 activity." (PMID 32673397, 2020). "Altogether, our data implicated a TKS5/FGD1/CDC42 axis in the polarization of MT1-MMP storage vesicles required for the persistent and efficient migration of breast cancer cells in a dense 3D matrix environment." (PMID 32673397, 2020). "Altogether, our work highlights a new, potentially druggable, molecular polarity feed-forward loop framework based on the interplay of TKS5, FGD1, and CDC42 function in the regulation of invadopodia activity as an essential axis of the MT1-MMP–based metastatic program of breast cancer cells." (PMID 32673397, 2020). "In addition, it was recently shown that FGD1, which is functionally related to FGD4, is up-regulated in human prostate and breast cancer, and regulates cancer cell invasion by modulating Cdc42 activation in a cell model." (PMID 22589722, 2012).
melanoma (5 papers, 2020 to 2024). A malignant, usually aggressive tumor composed of atypical, neoplastic melanocytes. "The X‐linked cancer‐related genes that have been associated with melanoma include ZNF280C, IL3RA, PNMA3, NHS, and FGD1." (PMID 38827026, 2024). "Knockdown of FGD1 inhibited melanoma cell migration, invasion, proliferation and colony formation, and promoted the expression of apoptosis-related genes." (PMID 34783295, 2021). "In this study, FGD1 was found to be significantly upregulated in melanoma tissue and the expression of FGD1 was related to the survival of melanoma patients." (PMID 34783295, 2021). "Next, a metastasis model was employed to assess FGD1-knockdown of lung tumorigenesis after tail vein injection of melanoma cells." (PMID 34783295, 2021). "In this study, with the use of bioinformatic tools, q-PCR and IHC, FGD1 was found to be highly expressed in melanoma tissues." (PMID 34783295, 2021). "After the knockdown of FGD1 in melanoma cells, the proliferation, migration, and invasion of cells were analyzed by cell counting kit-8 (CCK8) assay, colony formation assays and transwell assays." (PMID 34783295, 2021). "The results showed that the downregulated expression of FGD1 significantly inhibited the growth of melanoma in vivo." (PMID 34783295, 2021). "The results showed that knockdown of FGD1 significantly decreased proliferation, migration, invasion and colony formation of melanoma cells." (PMID 34783295, 2021). "FGD1 has been verified that it plays a direct role in the proliferation or invasion of melanoma cells, thereby the patients with high FGD1 expression frequently showed worse prognosis." (PMID 33392203, 2020). "In conclusion, FGD1 was found to be over-expressed in melanoma and could be considered as an independent prognosis factor for SKCM patients." (PMID 34783295, 2021). "This study suggested that knockdown of FGD1 could block melanoma formation and proliferation by inhibiting PI3K/AKT signaling pathway." (PMID 34783295, 2021). "Meanwhile, knockdown of FGD1 suppressed the development of melanoma in vivo." (PMID 34783295, 2021). "It was hypothesized that knockdown of FGD1 could refrain melanoma cell proliferation, migration, and invasion by inhibiting PI3K/AKT signaling pathway." (PMID 34783295, 2021). "In addition, nude mice models were used to study the role of FGD1 in melanoma development and metastasis in vivo." (PMID 34783295, 2021). "Knockdown of FGD1 inhibited melanoma cell proliferation, migration, and invasion." (PMID 34783295, 2021). "Compared with the control group, knockdown of FGD1 inhibited melanoma cell migration and invasion." (PMID 34783295, 2021). "Knockdown of FGD1 could inhibit melanoma cell proliferation, colony formation, migration, and invasion." (PMID 34783295, 2021). "A subcutaneous xenograft model was constructed to identify the role of FGD1 in melanoma." (PMID 34783295, 2021). "Collectively, FGD1 may serve as a potential therapeutic target in melanoma and may provide more information for personalized medicine." (PMID 34783295, 2021). "In the current study, bioinformatics analysis found that FGD1 could serve as a key gene in melanoma progression." (PMID 34783295, 2021). "Besides, FGD1 was also overexpressed in melanoma and had a close relationship with the prognosis in melanoma patients." (PMID 32194840, 2020). "Consistently, the GEPIA web tool analysis demonstrated that FGD1 mRNA expression was also positively correlated with PD-L1 mRNA in various types of tumors, including sarcoma, prostate cancer, pancreatic cancer, esophagus cancer, bladder cancer and melanoma." (PMID 32194840, 2020). "Thus, the expression level of FGD1 was knock downed by shRNA in two melanoma cell lines." (PMID 34783295, 2021). "Thus, it was assumed that FGD1 might play an important role in melanoma formation and progression." (PMID 34783295, 2021).
melanoma (continued). "In the current study, we found that higher expressions of FGD1, CSNK1E, and IRX3 are correlated with shorter survival of melanoma patients." (PMID 34769455, 2021). "By analyzing the TCGA genomics, we also found that the gene alteration rates in the melanoma TCGA dataset were 12% for DDX60, 5% for CSNK1E, 2.8% for FGD1, 2.1% for GBP4, 4% for IFIH1, 1% for DOK1, and 0.7% for IRX3, and these alterations were not significantly correlated with mRNA expression." (PMID 34769455, 2021).
osteosarcoma (5 papers, 2020 to 2022). A usually aggressive malignant bone-forming mesenchymal neoplasm, predominantly affecting adolescents and young adults. "In conclusion, our study revealed that FGD1 was aberrantly overexpressed in osteosarcoma specimens and associated with unfavorable prognosis." (PMID 32194840, 2020). "As FGD1 is responsible for the osteosarcoma tumor cell progression, the mechanism underlying the modulation of this process by FGD1 needs to be studied further." (PMID 32194840, 2020). "FGD1 inhibition profoundly decreased the osteosarcoma tumor cell proliferation ability in vitro, as revealed by the MTS assay and colony formation assay." (PMID 32194840, 2020). "Then, we stained FGD1 and PD-L1 in the osteosarcoma tissue microarray (n = 80) by IHC to investigate the correlation between FGD1 and PD-L1." (PMID 32194840, 2020). "Functional assays, such as the MTS assay, colony formation assay and xenografts, were used to determine the biological role of FGD1 in osteosarcoma." (PMID 32194840, 2020). "Then, we demonstrated that FGD1 was also abnormally up-regulated in osteosarcoma with unfavorable prognosis." (PMID 32194840, 2020). "In contrast, ectopically overexpressed FGD1 led to an increase in the IC50 values of MK2206 in three osteosarcoma tumor cell lines." (PMID 32194840, 2020). "At last, the survival assay performed using the GEPIA web tool indicated that over-expression of FGD1 shortened the disease-free survival time (Logrank P = 0.065) and overall survival time (Logrank P = 0.0024) of osteosarcoma patients." (PMID 32194840, 2020). "Collectively, our data suggest that FGD1 promotes the osteosarcoma tumor cell progression in vivo and in vitro." (PMID 32194840, 2020). "Meanwhile, we also found that knockdown of FGD1 blocked the tumor cell migration and regulated the cell cycle in osteosarcoma cells." (PMID 32194840, 2020). "PTEN knockdown up-regulated protein and mRNA levels of PD-L1 and most importantly attenuated the decreasing/increasing PD-L1 expression effect induced by FGD1 repression/overexpression in osteosarcoma tumor cells, respectively." (PMID 32194840, 2020). "In this study, we demonstrated that the N-terminal region of PTEN containing the phosphatase domain interacted with FGD1 in osteosarcoma tumor cells." (PMID 32194840, 2020). "On the contrary, FGD1 overexpression after transfection with FGD1 plasmids resulted in an increasing tumor cell growth in osteosarcoma cells." (PMID 32194840, 2020). "Faciogenital Dysplasia 1 (FGD1) was involved in multiple biological processes, such as cell cycle progression and cell polarity, and exhibits oncogenic behaviors in hepatocellular carcinoma and osteosarcoma." (PMID 34769455, 2021). "Aberrant expressed FGD1 promoted the osteosarcoma tumor cell proliferation and invasion." (PMID 32194840, 2020). "FGD1 contributed to osteosarcoma tumor cell proliferation and invasion in vivo and in vitro." (PMID 32194840, 2020). "Furthermore, we stained FGD1 in the osteosarcoma tissue microarray (osteosarcoma specimens n = 80) and found that FGD1 expression was positively correlated with the tumor stage." (PMID 32194840, 2020). "Collectively, we could demonstrate that FGD1 is capable of regulating the immune response via the PTEN/PD-L1 axis in osteosarcoma." (PMID 32194840, 2020). "Moreover, our data indicated that FGD1 promoted osteosarcoma progression by increasing the proliferation and invasion ability of the tumor cells." (PMID 32194840, 2020). "Besides, knockdown of FGD1 led to the osteosarcoma tumor cells being more sensitive to pan-AKT inhibitors (MK2206), as depicted by the decreasing IC50 values of MK2206 in three cell lines." (PMID 32194840, 2020). "Here, we revealed that abnormally overexpressed FGD1 promoted osteosarcoma progression." (PMID 32194840, 2020). "Together, the results demonstrate that FGD1 is up-regulated in osteosarcoma and could be used as a biomarker to predict the prognosis of osteosarcoma in patients." (PMID 32194840, 2020).